LATS1 (large tumor suppressor kinase 1)
Diseases named in the same sentence as LATS1 in open-access papers (continued):
Sharing a sentence is not in itself a finding about the gene and the disease.
tumor (continued). "Autonomous activation of the transcriptional effector TAZ was observed in LATS1/2-deleted cells along with non-autonomous activation within the evolving tumor niche." (PMID 39953252, 2025). "Moreover, YAP hyperactivity induced by LATS1/2 double-conditional knockout or YAP5SA expression through Nex-Cre results in an increased number of ependymal-like cells resembling ependymoma, a tumor of ependymal cells." (PMID 39936032, 2025). "Additionally, temporal analysis of SMGs identified LATS1 as a significant gene in early NMIBC evolution, consistent with its known role as a tumor suppressor in the hippo signaling pathway in BCa." (PMID 40247187, 2025). "Future therapeutic strategies could aim to restore tumor-suppressive inputs (e.g., by targeting FAT1-mediated signaling or GPCRs that activate LATS1/2) or directly inhibit the oncogenic YAP/TAZ-TEAD axis." (PMID 41256331, 2025). "Interestingly, NF2, a key tumor suppressor, responsible for activation of LATS1 (Large tumor suppressor homolog 1) and increased YAP1 phosphorylation, was significantly up‐regulated after silencing of TRIM65 expression." (PMID 39005234, 2024). "The LATS1 and MST1 were identified as tumor suppressor genes while regulating YAP phosphorylation." (PMID 37548821, 2023). "YAP is an oncogenic transcriptional coactivator, which is turned off in non-transformed cells by tumor suppressive Hippo/LATS1/2 signaling and conversely upregulated in tumor cells." (PMID 37686402, 2023). "Moreover, there are more than one E3 ubiquitin ligase for LATS1, further investigations are needed to characterize other CUL4A adaptors or additional E3 ligases in the regulation of tumor progression by S100A16." (PMID 37151881, 2023). "Since YTHDF2 destabilized LATS1 mRNA by reading the m6A methylation in LATS1, we predicted that deleting the expression of YTHDF2 could promote the tumor-suppressive effects of LATS1." (PMID 36609396, 2023). "Since LATS1 is a tumor suppressor in GC, targeting its upstream regulators, such as WWP2, to increase LATS1 expression could be an ideal therapeutic strategy." (PMID 36803368, 2023). "Based on our findings and others’, we speculate that WWP2-mediated LATS1 ubiquitination and subsequent YAP1 activation may promote tumor progression, thereby providing novel targets for clinical cancer therapy." (PMID 36803368, 2023). "Moreover, recent pancancer studies by The Cancer Genome Atlas Research in 9125 tumor samples have revealed that Hippo pathway components are widely altered in human cancers, such as downregulation of NF2, FAT1, TAOK1-3, WW45, and LATS1/2." (PMID 37211598, 2023). "Par3 promotes tumor growth through the interaction between PP1A and the Hippo pathway kinase Lats1 to induce Lats1 dephosphorylation and inactivation in response to cell contact and cell polarity signals, thereby leading to the dephosphorylation and activation of TAZ in the cytoplasm." (PMID 35875120, 2022). "However, KIBRA antibody, Merlin protein, and LATS1 and LATS2 kinase were slightly expressed in tumour cells (16.7%, 15.0%, and 15.0%, respectively)." (PMID 36552980, 2022). "miR-29c-3p inhibits tumor progression by regulating the methylation of DNMT3B and LATS1 in LIHC." (PMID 35574298, 2022). "Tumor cells lacking LATS1/2, a Hippo pathway kinase, have produced exosomes rich in nucleic acid boosting tumor immunogenic behavior." (PMID 35813829, 2022). "By contrast, RASSF1A, an upstream activator of MST2, and LATS1, a downstream substrate of MST2, may work as tumour suppressors." (PMID 36038253, 2022). "In the few mice where spontaneous tumorigenesis was absent or delayed, 4-HT administration to BrafV600E/Lats1/2−/− flanks resulted in the potent form of tumors which appeared histologically similar to the spontaneously arising neoplasms." (PMID 35768444, 2022). "We propose a tumor suppressor role for YAP1 and LATS1/2 in parathyroid tumors." (PMID 33670622, 2021).
tumor (continued). "When ACTN1 was knocked down, MOB1 could interact with LATS1, then increase the phosphorylation of LATS1/YAP and activate Hippo signaling, which led to the inhibitory effects on the tumor growth of HCC." (PMID 33413564, 2021). "Further studies in multiple human cell lines confirmed that SHANK2 overexpression causes deregulation of Hippo signaling through competitive binding for a LATS1 activator, and as a potential oncogene, SHANK2 promotes cellular transformation and tumor formation in vivo." (PMID 32661924, 2021). "The markedly increased protein expression of MST1, p-LATS1, p-YAP, and YAP (cytoplasm) and the significantly decreased expression of HIF-1α, TAZ, YAP (cells), and YAP (nucleus) in the tumor tissues of the sh-GHET1 group were compared with those of the sh-NC group." (PMID 33869194, 2021). "They showed that by deleting LATS1 and LATS2 (large tumor suppressor 1 and 2), tumor immunogenicity was modulated by enhancing the content of nucleic acid released in extracellular vesicles (EVs) by tumor cells." (PMID 34944765, 2021). "The core components of the canonical Hippo pathway are two kinase complexes: the first is the sterile 20-like kinase (MST1/2) and the second involves the large tumor suppressors LATS1 and LATS2 (LATS1/2), the adaptor Salvador homolog 1 (SAV1), and the MOB kinase activator (MOB1A-B)." (PMID 33802575, 2021). "Upon inspection of LATS1/2 cKO mice at P0–P21 age groups, we found that 67% at P5–P7 and 100% at P8–P21 developed tumours whereas no tumours were found before P5." (PMID 32404936, 2020). "Compared with H7;Lats1/2mut3 mice, H7;Lats1/2mut3;YAP/TAZmut4, H7;Lats1/2mut3;YAP/TAZmut3, and H7;Lats1/2mut3;YAP/TAZmut2 mice exhibited a YAP/TAZ dosage–dependent increase in time to tumor onset and decrease in tumor number." (PMID 32960816, 2020). "We observed similar results in multiple H7;Lats1/2mut3;YAP/TAZmut4 tumor–derived cell lines." (PMID 32960816, 2020). "The non-sRCCs were predominantly higher risk tumours; only 14 of the 268 (5%) had Hippo pathway alterations, involving NF2 (6/268), FAT1 (3/268), LATS1 (2/268), LATS2 (3/268) and YAP1 (1/268)." (PMID 31959902, 2020). "LATS1 and YAP expression levels in tumor tissues were downregulated and upregulated, respectively." (PMID 30718452, 2019). "Although not with significance, a trend of higher LATS1 mRNA expression was found in pre-treatment tumor tissues in patients not responding to Srf therapy as compared with Srf therapy responders." (PMID 31848340, 2019). "Therefore, enhanced immunogenicity unmasked by the LATS1/2 deletion in cancer cells induces strong immune responses and overwhelms any growth advantage that might be gained due to LATS1/2 deletion, leading to a strong inhibition of tumor growth in the immune-competent host." (PMID 31052239, 2019). "Recent studies revealed Hippo signaling as the major target of PTPN14 for tumor suppression, which mainly relies on the intermolecular interaction between the PPxY domain of PTPN14 and YAP or large tumor suppressor 1 (LATS1), key Hippo signaling pathway components." (PMID 31323018, 2019). "Loss of LATS1 is sufficient to drive deregulation of SOX2+ pituitary stem cells, generating highly proliferative non-functioning tumours with features of carcinomas." (PMID 30912742, 2019). "Altogether, this suggests that down-regulation of LATS1, but not LATS2, favors partial loss of luminal identity of tumor cells." (PMID 30456386, 2018). "A melanoma cell line lacking Hippo pathway components Lats1/2 was shown to induce anti-tumor immune responses in a syngeneic mouse model." (PMID 29673177, 2018).
tumor (continued). "The transcriptional coactivator YAP is a major downstream negative effector of the Hippo pathway 6, 7 and is tightly negatively regulated by a series of upstream components such as NF2, LATS1/2, MST1/2 and SAV1, which are tumour suppressors in several types of human cancers." (PMID 28470935, 2017). "To reveal the physiological role of this negative feedback regulation, we deleted Lats2 or Lats1 in the liver-specific Sav1-knockout mouse model which develops a YAP-induced tumor." (PMID 27006470, 2016). "While the core module members MST1/2, Salvador, LATS1/2 and MOB1 have been attributed tumour suppressive functions, YAP/TAZ have been mainly described to have oncogenic roles, although some reports provided evidence supporting growth suppressive roles of YAP/TAZ in certain cancer settings." (PMID 25097725, 2014). "Unfortunately, the lack of LATS1/2 animal studies has hindered the definition of how far the MST1/2-SAV-MOB1-LATS1/2-YAP axis is responsible for tumour formation in transgenic MST1/2, SAV, MOB1, or YAP mice." (PMID 25097725, 2014). "Yet, the role of LATS1 as a tumor suppressor does not necessarily mean that elevated expression of LATS1 would hinder cell proliferation and prevent tumor growth, as demonstrated here and in another study." (PMID 19656388, 2009). "Upon phosphorylation by Mst1/2 and Lats1/2, YAP/TAZ dephosphorylates and dissociates from cytoplasmic 14-3-3 kinase to enter the nucleus where it interacts with TEAD and other factors to initiate transcriptional expression of downstream target genes and promote stemness maintenance in tumor CSLCs." (PMID 38634107, 2024). "Multiple negative regulators of YAP identified under physiological conditions, such as cytoplasmic MST1/2, LATS1, and MST4, as well as nuclear factors VGLL4 and RUNX3, were found to be dramatically reduced or inactivated during GC development, resulting in YAP-dependent GC tumor growth." (PMID 36924251, 2023). "Specifically, LATS1/2-null or YAP/TAZ-activated tumor cells could secrete nucleic acid-rich extracellular vesicles that stimulated the host TLR-MYD88/TRIF-IFN pathway to induce antitumor immunity and the eventual elimination of tumor cells." (PMID 37211598, 2023). "Furthermore, these data suggest that reduced activity of Hippo-kinases such as LATS1 and LATS2 could serve to circumvent RASSF1A-mediated tumor suppressive mechanisms." (PMID 34831091, 2021). "Furthermore, deletion of an endogenous YAP and TAZ negative-regulator, LATS1/2, in the surrounding tissue significantly reduced tumor burden, indicating that heightened YAP in the peritumoral tissue can restrain tumor growth." (PMID 33430180, 2021). "The hypothesis is that the downregulation of LATS1 enhances ROS production, promoting an intrinsic hypoxia state with elevated AOX1 expression, which upregulates cancer stem cell marker CD133 resulting in enhanced tumor growth." (PMID 33803640, 2021). "In LATS1/2; YAP1f/f mice, tumours were negative for YAP1 immunostaining supporting its specificity." (PMID 32404936, 2020). "Therefore, we speculated that Apatinib could lessen the expression of oncogene YAP/TAZ, which in turn relieves the inhibition of the tumor suppressor genes MST1/2 and LATS1/2; they may also play roles at the same time in the process Apatinib works." (PMID 32849930, 2020). "Although LATS1 and 2 and YAP/TAZ signaling has been implicated in tumorigenesis, these findings are largely based on experimental models which modulate LATS1 and 2 and/or YAP/TAZ signaling within the tumor cell, not within the endothelium." (PMID 33304925, 2020). "Multiple clonal forebrain tumours, originating invariably at the ependymal layer were found in all LATS1/2 cKOs, but not in controls or individual LATS1 cKOs or LATS2 cKO at P20 (18/18 dual knockout, 0/3 LATS1 cKO, 0/3 LATS2 cKO, 0/6 controls), indicating redundancy between LATS1 and LATS2." (PMID 32404936, 2020).
tumor (continued). "In our LATS1/2 cKO mouse model, although some of the tumour markers were highly present in the centre of the tumour mass, e.g., ANKRD1, Vimentin, CK18, nestin and Ki67, some were localised towards the edges of the tumour, e.g., HOPX, AMOTL2, AXL and microglial marker C3." (PMID 32404936, 2020). "Moreover, although shRNA-mediated loss of LATS1 did not affect primary tumor growth of HCC cells in xenotransplanted immunodeficient mice, it significantly reduced tumor growth under Srf treatment." (PMID 31848340, 2019). "SOX2+ pituitary stem cells are the cell-of-origin of tumours generated in the absence of Lats1." (PMID 30912742, 2019). "To recapitulate the tumorigenic phenotype shown in the mouse model in which negative feedback on YAP/TAZ is ablated, we characterized tumor-associated cellular phenotypes in the AML-12 normal mouse liver cell line after depletion of SAV1, LATS1, and/or LATS2 proteins with shRNA constructs." (PMID 27006470, 2016). "Furthermore, we chose several EZH2 or LSD1 potential targets (P15, P21, LATS1, LATS2, RND1, KLF2, E-cadherin, PTEN, ASPP2 and RRAD) with tumor-suppressor function, and hypothesized that they may involve in the contributions of AGAP2-AS1 to NSCLC progression." (PMID 27195672, 2016). "Moreover, the expression of LATS1 was inversely correlated with the YAP expression and lymphatic invasion of the tumour, indicating that LATS1/YAP signalling may participate in the progression of LAC." (PMID 25712415, 2015). "The observation that LATS1/2 KO by CRISPR/Cas9 confers resistance to EGFR inhibitors in vitro and in vivo indicate that YAP/TAZ reactivation by an unknown mechanism after EGFR inhibitor treatment plays an important role in HNSCC initial resistance or tumor recurrence." (PMID 36294681, 2022). "However, since Hsp90 also chaperones some tumor suppressive proteins such as interferon regulatory factor 1, LATS1 and LATS2 kinases, shepherdin’s inhibition on Hsp90 might deregulate tumor suppressor pathways, which might be one of the reasons why shepherdin failed in clinical application." (PMID 32381104, 2020). "The nYAP/cYAP pattern might reflect YAP activity in a tumor: YAP has transcription-promoting activity only when it is localized in the nucleus and is presumably transcriptionally inactive when it is retained in the cytoplasm and is phosphorylated at S127 by LATS1/2." (PMID 24622501, 2014). "While conventional cancer driver genes of sporadic PC were not involved in our case, deletions were identified in the tumor suppressor genes CDKN2A, LATS1, ARID1A, and ARID1B." (PMID 40362680, 2025). "In same regard, the lack of LATS1/2 reduced the inhibitory effects of the STARD13-correlated ceRNA network on EMT features of CSC, indicating that the tumor-suppressive effects of the STARD13-correlated ceRNA network are mediated by LATS1/2 modulation." (PMID 39170516, 2024). "We observed in tumour samples that AURKA inhibition does not influence the expression and phosphorylation levels of LATS-1 and MOB-1, main effectors of the Hippo-dependent YAP1 phosphorylation at Ser397." (PMID 38467828, 2024). "warts encodes a serine/threonine kinase working in the hippo pathway and its human counterpart, large tumor suppressor kinase 1 (LATS1)), is a tumor suppressor involved in the negative regulation of CDC2 kinase activity." (PMID 35682766, 2022). "VT02956 treatment had marginally effect on the growth of LATS1/2 dKO nor YAP/TAZ dKO cells, demonstrating that VT02956 targets the LATS-YAP/TAZ-ERα axis to inhibit ER+ tumours cell growth." (PMID 35217640, 2022). "Knockout of YAP/TAZ and their TEAD cofactors inhibited HPAF-II tumor cell proliferation, whereas knockout of their negative regulators SAV1 and LATS1 promoted in vivo (but not in vitro) tumor growth." (PMID 35536676, 2022).
tumor (continued). "Regarding B-cell infiltrates, which have been shown to play a role in promoting the anti-tumor immune response, interestingly, MPM tumors harboring LATS1/2 rather than NF2 display enriched plasma B-cell signature." (PMID 33805359, 2021). "We found that all LATS1/2 cKO animals where one or both copies of YAP1 was deleted still exhibited tumours at P20 (n = 3 each), indicating that YAP1 is not the sole downstream factor regulated by LATS1/2." (PMID 32404936, 2020). "Analysis of proliferation by Ki-67 immunostaining revealed an elevated mitotic index of 7–28% in tumours (mean 15.46, SEM ±2.74), compared to 2.97% (SEM ±1.2) mean in control pituitaries not carrying the Lats1 deletion." (PMID 30912742, 2019). "Membrane recruitment of LATS1/2 by Merlin facilitates YAP phosphorylation that occurs irrespective of MST1/2 activation, and tumor suppressive activities are ensued." (PMID 29415512, 2018). "Using these MOB1 variants with selective loss-of-interaction, we found that a stable interaction of MOB1 with LATS1/2, but not with MST1/2, is essential for tumor suppressive properties of MOB1 in human cancer cells." (PMID 28947795, 2017). "Such an analysis of human large tumor suppressor genes, LATS1 and LATS2, has been carried out and the results support a role of hLATS1//2 as negative growth regulators and tumor suppressors." (PMID 25482410, 2015). "The expression of LATS1 and YAP was correlated with lymphatic invasion of LAC (P + 0.015, P + 0.003), but they did not link to other factors including age, gender, tumour size, pathological stage and TNM stage (each P > 0.05)." (PMID 25712415, 2015). "Although YAP/TAZ usually promote the expression of genes related to tumor promotion, early studies also showed that YAP/TAZ activation induced the transcription of their negative regulators, including LATS1/2, AMOT, and NF2, to establish a negative feedback loop and prevent tumorigenesis." (PMID 37211598, 2023). "Additionally, MST2 is involved in the LATS tumor suppressor pathway via complexation with hSav, RASSF1A, Nore1 and LATS1, resulting in the phosphorylation of LATS1 and transcription of proapoptotic genes." (PMID 20730082, 2010). "We found that S100A16 did not affect MST1/2 expression, but decreased LATS1 protein and MOB phosphorylation, which allowed YAP to enter the nucleus triggering the downstream targets CYR61 and CTGF, which are known to stimulate the angiogenesis and tumor growth 29,30." (PMID 37151881, 2023). "In line with this, the absence of LATS1/2 attenuated the inhibitory roles of STARD13-correlated ceRNA network on CSC and EMT traits, highlighting that STARD13-correlated ceRNA network exerts its tumor-suppressive effects at least partly through regulating LATS1/2." (PMID 29848346, 2018).